C9orf72 (C9orf72-SMCR8 complex subunit)
Diseases named in the same sentence as C9orf72 in open-access papers (continued):
Sharing a sentence is not in itself a finding about the gene and the disease.
Autoimmunity (16 papers, 2016 to 2025). The occurrence of an immune reaction against the organism's own cells or tissues. "Loss-of-function (LoF) mutations in C9orf72 leads to severe autoimmunity and premature mortality in mouse models." (PMID 37307819, 2024). "Most importantly, the study of SMCR8 knockout mice has revealed that they develop autoimmunity similarly to C9ORF72 deficient animals, but they also display mild motor phenotypes resembling those observed in C9ORF72 knockout mice and in our model." (PMID 37138765, 2023). "Following these findings, it was later discovered that FTD patients with C9orf72 mutations had a substantially increased risk of being diagnosed with an autoimmune disorder prior to their brain condition." (PMID 36406749, 2022). "prevents C9orf72-mutant mice from early death and positively influences their underlying systemic inflammation and autoimmunity." (PMID 36406749, 2022). "Meanwhile, a recent study found that mutations disrupting the normal function of C9orf72 cause mice to develop features of autoimmunity." (PMID 33541344, 2021). "For example, loss of C9orf72 triggered a hyperactive type I interferon response with enhanced autoimmunity and anti-tumor immunity in mice." (PMID 34281203, 2021). "To study the organismal and cellular functions for this tripartite complex, we generated Smcr8 loss-of-function mutant mice and found that they developed phenotypes also observed in C9orf72 loss-of-function animals, including autoimmunity." (PMID 29950492, 2018). "Previously, we and others found that loss-of-function mutations in the mouse C9orf72 ortholog resulted in autoimmunity." (PMID 29950492, 2018). "Several groups showed that complete ablation of C9ORF72 causes mice to develop autoimmunity." (PMID 37138765, 2023). "Ultimately, epidemiological cohort studies such as these require larger numbers of genetically and pathologically confirmed patients and further research targeted at determining the molecular mechanisms underlying a relationship between autoimmunity, C9orf72, and FTD/ALS is required." (PMID 34360544, 2021). "C9orf72 expansion has been the focus of multiple rodent model studies demonstrating that loss or elimination of C9orf72 function profoundly disturbs immune homeostasis and predisposes to autoimmunity, therefore implicating C9orf72 in the regulation of autoimmunity." (PMID 34360544, 2021). "Experimental studies investigating C9orf72 loss-of-function in C9orf72-deficient mice revealed an increase in proinflammatory cytokines, lymphadenopathy, splenomegaly, alterations in myeloid cells from spleen, and in some cases of autoimmunity." (PMID 30774737, 2019). "Although mainly implicated in neurodegenerative disorders, the human gene C9orf72 is highly expressed not only in microglia but also in myeloid cells, mainly monocytes and dendritic cells, is critical for their proper functions and is involved in autoimmunity and inflammation." (PMID 34209673, 2021). "The loss of C9orf72 in myeloid cells hinders STING protein degradation via the autolysosomal pathway, leading to hyperactive type I IFN responses and autoimmunity." (PMID 37307819, 2024). "This study also confirmed high expression of C9orf72 in immune cells, which links in with the strong phenotype of autoimmunity and inflammatory disease in C9orf72 knockout mice." (PMID 35573690, 2022). "Microbiota seems to be a potent modifier of onset and progression of autoimmunity, inflammation and premature mortality in C9orf72−/− knockout mice." (PMID 34209673, 2021). "As it has been shown that C9orf72−/− mice developed autoimmunity, we first looked for signs of autoimmunity in the Smcr8 mutant mice." (PMID 29950492, 2018). "In summary, our results implicate loss of mouse C9orf72 expression with autoimmunity that resembles human SLE and suggest a new role for C9ORF72 as an important regulator of the immune system." (PMID 26979938, 2016).
Autoimmunity (continued). "C9orf72 homozygous knockout mouse models manifest severe autoimmunity and lymphatic defects, indicating a role for C9orf72 in immune cell function, but there are no striking alterations in heterozygous knockouts which more closely resemble the level of C9orf72 depletion in patients." (PMID 38424324, 2024). "In SMCR8 and in C9ORF72 deficient mice, promoting autophagy via MTOR inhibition could rescue the autoimmunity phenotype, definitely establishing a causative link between the cellular function of C9ORF72 and immune dysfunction." (PMID 37138765, 2023). "While gene-editing approaches can have off-target effects, our findings would seem to resolve any lingering doubt concerning whether C9orf72 and its molecular collaborator, Smcr8, normally function to suppress autoimmunity." (PMID 29950492, 2018). "In addition, we produced Smcr8 loss-of-function mutant mice and found that they exhibited central phenotypes observed in C9orf72 mutant animals, including autoimmunity." (PMID 29950492, 2018). "Therefore, we concluded that, similar to previous observations in C9orf72 mutant animals, autoimmunity was the most probable underlying cause of enlarged lymph nodes and splenomegaly seen in the Smcr8 CRISPR F0 mice." (PMID 29950492, 2018). "Thus, C9orf72 might serve as an important factor related to inflammation and autoimmunity." (PMID 33541344, 2021). "C9ORF72 and SMCR8 have interdependent functions in suppressing autoimmunity and negatively regulating lysosomal exocytosis." (PMID 34360544, 2021). "Overall, our findings demonstrate that C9ORF72 and SMCR8 have interdependent functions in suppressing autoimmunity as well as negatively regulating lysosomal exocytosis—processes of potential importance to ALS." (PMID 29950492, 2018). "While still suggesting a role of C9orf72 in immunoregulation, this study did not provide support for the specific association between TDP-43 pathophysiology and autoimmunity." (PMID 34360544, 2021).
myotonic dystrophy type 1 (16 papers, 2017 to 2024). Steinert disease, also known as myotonic dystrophy type 1, is a muscle disease characterized by myotonia and by multiorgan damage that combines various degrees of muscle weakness, arrhythmia and/or cardiac conduction disorders, cataract, endocrine damage, sleep disorders and baldness. "Southern Blotting has been a gold standard technique for measuring allele sizes in various conditions such as C9orf72 repeat expansion disorders, myotonic dystrophy type 1 (DM1), and fragile X syndrome." (PMID 37892228, 2023). "A low copy number for a disease-causing RNA has also been observed for myotonic dystrophy type 1(DM1) and C9orf72 ALS/FTD." (PMID 32463444, 2020).
cognitive decline (15 papers, 2018 to 2025). "Cognitive decline in language, and attention and mental processing speed was already present in the presymptomatic stage of C9orf72 mutation carriers, and in executive function in GRN mutation carriers, albeit to a lesser extent than in the symptomatic stage." (PMID 39500348, 2024). "We compared cognitive profiles cross-sectional in patients with bvFTD due to mutations in GRN, MAPT or C9orf72 and report patterns of cognitive decline in a subset of patients with follow-up data." (PMID 32052166, 2020). "Genetic studies that included a search for the commoner mutations causing cognitive decline revealed three patients with mutations; there were pointers to the correct diagnosis in all three (C9orf72 and CSF1R) on neurophysiology testing and MRI." (PMID 29142140, 2018). "In summary, we have generated the first unbiased map of the human ALS synaptic proteome, revealing novel insight into this key compartment in ALS pathophysiology and highlighting the influence of cognitive decline and C9ORF72-RE on synaptic composition." (PMID 36309735, 2022). "In addition, MAPT mutation carriers are known for their rapid cognitive decline once they become symptomatic, probably causing lower performance on neuropsychological tests compared to patients with a GRN or C9orf72 mutation in their early symptomatic stages." (PMID 39229325, 2024). "Increased abundance of proteins identified within the inflammatory co‐expression module in the frontal cortex of ALS/FTD, FTD, and C9Pos ALS cases may explain the clinical link between cognitive decline and the C9orf72 expansion." (PMID 29191947, 2018). "Similarly, exploratory longitudinal descriptions provided valuable information on rate of cognitive decline with indeed rapid cognitive decline in GRN, but slow progression in C9orf72 and MAPT showing intermediate decline." (PMID 32052166, 2020).
psychosis (15 papers, 2016 to 2025). "This is a case summary of a 42-year-old male with a rapidly progressive FTD-ALS caused by a pathogenic repeat expansion of GGGGCC in the C9orf72 gene, which presented with psychosis and disorganized behavior leading to admission to psychiatry." (PMID 37548032, 2024). "In patients with FTD or ALS, late-onset psychotic disorders as the initial presentation have been reported to be more frequent when these diseases are secondary to the C9orf72 mutation." (PMID 37761400, 2023). "Hallucinations and delusions, as classic positive symptoms of psychosis, have received the most research interest with a prevalence of up to 50% reported in patients with ALS–FTD and C9orf72 associated ALS–FTD." (PMID 35279757, 2022). "Overall, late-onset psychosis should always raise concern for familiality with motor neuron disease and thus warrant genetic testing for c9orf72 repeat expansion." (PMID 30914912, 2019). "Genetic evidence of overlap to date has been based primarily on individual genes showing Mendelian inheritance, in particular the C9orf72 hexanucleotide repeat expansion, which is associated with ALS and FTD, and with psychosis in relatives of ALS patients." (PMID 28322246, 2017). "Delusions (but not hallucinations) are also more common in FTD-ALS than in bvFTD without ALS13 As such, it was interesting that in this case (c9orf72 positive FTD-ALS) the patient had visual hallucinations, as these are relatively rare in FTLD14 and in cases of psychosis amongst C9orf72 carriers." (PMID 37548032, 2024). "When analyzing the clinical feature best discriminating c9orf72 carriers from non-carriers in a cohort of bvFTD patients, psychosis and familiality for ALS appeared the most reliable clues." (PMID 30914912, 2019). "Such evidence appear to be even more consistent when referring to psychotic disorders, as well as in line with the current knowledge on schizophrenia spectrum disorders frequently occurring within the genealogical tree of ALS and FTD patients, possible due to C9orf72-related genotypes." (PMID 36053340, 2022).
Brain atrophy (14 papers, 2017 to 2025). Partial or complete wasting (loss) of brain tissue that was once present. "A recent study explored co-expression patterns associated with brain atrophy patterns in symptomatic FTD mutation carriers in C9orf72, GRN, and MAPT and report top 20 genes and relevant biological pathways." (PMID 38469573, 2024). "This aligns with previous works demonstrating a faster progression rate of brain atrophy in individuals with pathogenic variants in GRN than those in C9orf72." (PMID 37609205, 2023). "This aligns with previous work demonstrating a faster progression rate of brain atrophy in individuals with pathogenic variants in GRN than those in C9orf72." (PMID 38062485, 2023). "Imaging study results showed asymmetric atrophy in the inferior frontal, temporal, and inferior parietal lobes, whereas C9orf72 or MAPT mutations are associated with symmetrical brain atrophy." (PMID 30846947, 2019). "Longitudinal data suggest that patients with pathogenic variants in GRN experience faster brain atrophy progression than those with pathogenic variants in C9orf72, indicating different rates of pathological progression and fundamental mechanisms associated with different gene variants." (PMID 37609205, 2023). "The small increases in the rate of volume loss in the C9orf72+ group prompted the question of whether expansions in this gene are associated with accumulation of brain atrophy to a similar degree as pathogenic variants in the other genes." (PMID 33112398, 2020). "It is also noteworthy that TDP-43 nuclear depletion, accompanied by brain atrophy and C9orf72-related pathology, were observed in the temporal lobe of a C9orf72 repeat expansion carrier following surgery for epilepsy." (PMID 35879741, 2022). "This implies that these cases have a more severe disease phenotype compared to non-C9/GRN FTLD, a hypothesis substantiated by previous studies which showed increased rates of decline in C9orf72 cases and greater brain atrophy in GRN cases." (PMID 28877758, 2017). "These shared genes that are commonly expressed in regions more spared by cortical atrophy in C9orf72-bvFTD and GRN-bvFTD, and conversely, these genes are commonly expressed in regions more vulnerable to brain atrophy in MAPT-bvFTD." (PMID 39920674, 2025). "C9orf72 ALS has a faster disease progression rate and shorter survival, reflecting a widespread CNS neurodegeneration and more severe brain atrophy that may explain higher pNfH concentration rather than a specific role of C9orf72." (PMID 33059698, 2020). "Conversely, shared genes with negative weights in C9orf72-bvFTD also displayed negative weights in GRN-bvFTD, suggesting that these genes were commonly expressed in regions more vulnerable to brain atrophy." (PMID 39920674, 2025).
fragile X syndrome (13 papers, 2016 to 2025). A genetic syndrome caused by mutations in the FMR1 gene which is responsible for the expression of the fragile X mental retardation 1 protein. "Similar methylation changes are observed in other repeat expansion disorders, including C9orf72‐related ALS/FTD26, 27 and Fragile X syndrome, where they have been linked to transcriptional dysregulation." (PMID 40459184, 2025). "In addition to C9orf72-linked disease R-loop formation has been characterized in several microsatellite disorders, such as Fragile X Syndrome (FXS) and Friedrich’s Ataxia (FRDA)." (PMID 28744202, 2017). "We reasoned that disrupting R-loop formation by depleting C9ORF72 mRNAs in iPSCs would prevent DNA hypermethylation upon neuronal differentiation, similar to what was previously shown in Fragile X Syndrome." (PMID 28606110, 2017). "We developed a PCR assay using primers flanking the C9orf72 HRE and applied the HPE PCR conditions developed for Fragile X syndrome." (PMID 27288208, 2016).
neuroblastoma (12 papers, 2016 to 2025). Neuroblastoma (NB) is the most common solid, extracranial childhood tumor. "GFP-GA5 (Control) and GFP-GA100 plasmids were transfected into N2a cells (mouse neuroblastoma cell line) to mimic the C9orf72-poly-GA model in vitro." (PMID 40860154, 2025). "More precisely, the authors tested C9orf72 promoter activity in human kidney and neuroblastoma cell lines and observed reduced C9orf72 transcription in cells with larger repeats and increased methylation." (PMID 30774737, 2019). "Here, we utilized knockdown or overexpression of C9orf72 in mouse N2a neuroblastoma cells or cultured neurons to elucidate the potential role of C9orf72 proteins in autophagy and UPS." (PMID 31658762, 2019). "Hence, the four C9orf72 DPRs examined here were found to display different cellular localizations in neuroblastoma cells, consistent with previous studies." (PMID 38722513, 2024). "Subsequent mass spectrometry-based proteomics of immunoprecipitates from neuroblastoma NSC-34 cells overexpressing human C9ORF72 identified cofilin, Arp2/3, coronin, Arf1, and Arf6 as novel C9ORF72 interactors." (PMID 35563476, 2022). "To examine whether gRNA1-2 affect C9ORF72 protein expression in cells derived from human brain, we employed U251 and SH-SY5Y, the human glioblastoma and neuroblastoma lines." (PMID 35383205, 2022).
schizophrenia (12 papers, 2012 to 2025). A major psychotic disorder characterized by abnormalities in the perception or expression of reality. "The schizophrenia pattern was expressed in 92 of 108 patients (85.5%) with bvFTD and was linked to the C9orf72 variant, oligoclonal banding in the cerebrospinal fluid, cognitive impairment, and younger age (R2 = 0.29)." (PMID 35921104, 2022). "C9orf72 hexanucleotide expansion has been associated to multiple traits including Alzheimer’s and Parkinson’s diseases, ataxia, chorea and schizophrenia." (PMID 33256133, 2020). "As previously highlighted, increased risk for schizophrenia and single psychotic episodes is observed among kindreds of c9orf72 carriers." (PMID 30914912, 2019). "An atypical neuropsychiatric presentation is also seen in C9orf72 carriers and family members of carriers are at greater risk of psychiatric disorders including schizophrenia and autistic spectrum disorders." (PMID 31119452, 2019). "Although rare, C9orf72 expansions have been implicated in other neurodegenerative and psychiatric diseases including PD and Schizophrenia, suggesting a wider role for C9orf72 in neuropathology and perhaps offering some insight towards the heterogeneous phenotype seen in C9orf72 ALS." (PMID 32610599, 2020). "The link between ALS and schizophrenia was further supported by a large genome-wide association study which found a substantial genetic correlation, only partially explained by pleiotropic gene variants such as c9orf72." (PMID 30914912, 2019). "A population-based GWAS study reported a higher prevalence of psychosis, suicidal behaviour, and schizophrenia, in Irish ALS kindreds, which was associated with the C9orf72 repeat expansion, based on an aggregation analysis." (PMID 33256133, 2020). "Bioinformatic analysis of C9ORF72 using the Gene Expression Omnibus database showed expression differences in patients with muscular dystrophy, neural tube defects, and schizophrenia." (PMID 23060854, 2012). "Another study demonstrated that C9ORF72 is overexpressed in cerebellar cortical samples from schizophrenia patients." (PMID 23060854, 2012). "C9orf72 carrier status (n = 11), oligoclonal banding in the cerebrospinal fluid (CSF), lower cognitive performance, younger age, and relatively reduced total CSF cell counts predicted higher schizophrenia scores." (PMID 35921104, 2022). "A neuropsychiatric prodrome has been described in some people with ALS–FTD, and higher rates of schizophrenia and suicide have been reported in first and second degree relatives of those with ALS, particularly in kindreds associated with the C9orf72 hexanucleotide repeat expansion." (PMID 28322246, 2017).